LRTM1 (leucine rich repeat transmembrane protein 1)
Synonyms: HT017
Tractability: Antibody: UniProt predicts a signal peptide or a membrane-spanning region.
Gene: Protein-coding gene on chromosome 3 (54,918,231 to 54,967,088, reverse strand). Ensembl gene ENSG00000144771.
Subcellular location: Membrane
Gene Ontology:
Molecular function: protein binding
Cellular component: membrane
Genetic constraint (gnomAD): Loss-of-function variants: 35 observed, 32.8 expected, observed/expected ratio (o/e) 1.07, 90% interval 0.81 to 1.41. The upper end of that interval is the gene's LOEUF score, 1.41, which puts it in group 5 of 6, group 1 being the genes least tolerant of losing a copy. Missense variants: 464 observed, 436.56 expected, observed/expected ratio (o/e) 1.06, 90% interval 0.98 to 1.15. Synonymous variants: 186 observed, 178.59 expected, observed/expected ratio (o/e) 1.04, 90% interval 0.92 to 1.18.
Homologues: Orthologues: chimpanzee LRTM1 (99% identical), macaque LRTM1 (93% identical), dog LRTM1 (80% identical), rabbit LRTM1 (78% identical), pig LRTM1 (77% identical), guinea pig LRTM1 (76% identical), mouse Lrtm1 (66% identical), zebrafish lrtm1 (43% identical), tropical clawed frog lrrc19 (23% identical). Paralogues in human: LRRTM3 (26% identical), LRRC4C (24% identical), RTN4R (24% identical), LRRC4B (24% identical), FLRT1 (23% identical), LRRTM4 (23% identical), FLRT2 (23% identical), LRRC4 (23% identical), RTN4RL2 (23% identical), LRRC15 (23% identical), FLRT3 (22% identical), LRRTM1 (22% identical), and 10 more.
Diseases named in the same sentence as LRTM1 in open-access papers:
LRTM1 is named in the same sentence as 1 disease in open-access papers, as found by Europe PMC text mining. Sharing a sentence is not in itself a finding about the gene and the disease. The quoted sentences say what the papers report.
tumor (2 papers, 2016 to 2024). "Additionally, CYP4F8, PDZD3, CRTAC1, and LRTM1 were identified as potential tumor suppressor genes." (PMID 38172792, 2024). "When transplanted into 6-OHDA-lesioned rats, human iPSC-derived LRTM1+ cells survive and differentiate into mDA neurons in vivo, resulting in a significant improvement in motor behaviour without tumour formation." (PMID 27739432, 2016).